TNF (tumor necrosis factor)
Diseases named in the same sentence as TNF in open-access papers (continued):
Sharing a sentence is not in itself a finding about the gene and the disease.
tuberculosis (continued). "In addition, reduced apoptosis in tuberculosis may be due to a higher production of IL-10 than TNF-α and NO, which is controlled by low expression of the SLC11A1 (formerly NRAMP) gene encoding macrophage protein 1, which is associated with natural resistance." (PMID 36982159, 2023). "Protection against tuberculosis (TB) requires a robust proinflammatory Th1-type immune response with cytokines like TNF and IFN-gamma being vital for cell recruitment and activation of microbicidal mechanisms, and granuloma formation to wall off the bacteria." (PMID 35976976, 2022). "In a novel randomized controlled study, the occurrence of tuberculosis was evaluated in patients receiving TNF-α inhibitors and exposure to TNF-α inhibitors was associated with a statistically significant threefold increase in the risk of TB." (PMID 35887523, 2022). "Most of the pathways, including HIF-1 signaling and HTLV-1 infection, for both of the herbs, are common, but the differences are Tuberculosis (TB) infectious disease, proteoglycans in cancer pathways in Honghua and TNF, influenza, pathways in Xihonghua." (PMID 35995784, 2022). "This study compared the incidence of TB after treatment with TNF inhibitors and tocilizumab in patients with RA, separately in those who were treated for latent tuberculosis infection (LTBI) and those without evidence of LTBI." (PMID 35761359, 2022). "The reduced secretion of TNF-α and IL-17 results in inability of the body to form granulomas thus promoting M. tuberculosis spread and development of generalized TB." (PMID 35804458, 2022). "Pathogenic mycobacteria can inhibit and/or regulate host cell TNF-α production in a variety of ways to evade antituberculosis (anti-TB) immunity as well as facilitate immune escape." (PMID 35651754, 2022). "Our pathway study identified seven virus-associated diseases, including influenza (tuberculosis, viral carcinogenesis, hepatitis B and C, toxoplasmosis, Epstein–Barr virus infection, and influenza) and three inflammation-associated pathways (PI3K-AKT, TNF, and MAPK signaling pathways)." (PMID 34577580, 2021). "NBXH upregulates Mapk14 expression, regulates the immune response during M. tuberculosis infection, induces BAX translocation and apoptosis, enhances TNF expression, limits M. tuberculosis, and exerts an anti-TB effect." (PMID 34074345, 2021). "In addition, we noticed that CAMP was mainly enriched in the following signaling pathways and biological processes: tuberculosis, innate immune response, cell redox homeostasis, cellular response to interleukin-1, and cellular response to tumor necrosis factor." (PMID 33758323, 2021). "When the secretion of IL-2 and TNF is insufficient, the immune response cannot completely eliminate M. tuberculosis but is increased with the improvement in TB after anti-TB treatment." (PMID 34074345, 2021). "The three in vivo-expressed Mycobacterium tuberculosis antigens, Rv2346/47c, Rv2431c, and Rv3614/15c and the DosR antigen Rv2031c induced significantly higher TNF-α and IP-10 responses in TB patients shortly before clinical diagnosis compared to controls." (PMID 33777000, 2021). "Despite the remarkable effectiveness of TNF inhibitors, however, reactivation of latent tuberculosis (TB) is a major safety concern." (PMID 34095175, 2021). "Thus, a baseline cytokine signature of TNFα, IL-2, and IL-17A could serve as an accurate biomarker for the diagnosis of pediatric tuberculosis." (PMID 33936077, 2021). "Possibility of tuberculosis (TB) reactivation over treatment with anti-tumor necrotizing factor (TNF) alpha agents has necessitated a screening test before initiation of treatment." (PMID 32615992, 2020). "Five tuberculosis (TB) AE have been reported in Taiwan in patients treated with anti-TNF-α, presenting an incidence rate of 354.3 people/year, an adjusted HR of 3.37 (95% CI: 1.12–10.17), and a rate of 6.85 per 1000 people/year." (PMID 32842558, 2020).
tuberculosis (continued). "Therefore, it is recommended to give antibiotic prophylaxis with oral trimethoprim/sulfamethoxazole (400 mg/125 mg 3 times a week) together with steroids and to test patients for tuberculosis before adding any additional immunosuppressive drug (e.g. TNF alpha inhibitors) to corticosteroids [85.]." (PMID 30707321, 2019). "It was indirectly noticed that the reactivation of tuberculosis during anti-TNF therapy may be associated with autophagy suppression, but the effect of TNF inhibitors on autophagy has not been investigated yet in vitro." (PMID 30696478, 2019). "We herein report a patient with reactive arthritis induced by active extra-articular tuberculosis, who experienced persistent peripheral inflammation in the limbs despite antitubercular treatment and was treated successfully with a tumor necrosis factor (TNF) inhibitor." (PMID 31804308, 2019). "The aim of the present study was to investigate the association of TNF-α-308 and TNF-α-238 gene polymorphisms with the risk of bone-joint and spinal tuberculosis (TB) by meta-analysis." (PMID 31072917, 2019). "The study claimed that the ability of the plant extracts to increase the IFN-γ, IL-6, and TNF-α production by leukocytes enabled eradication of mycobacteria in tuberculosis (TB) by inducing the release of NO." (PMID 31440162, 2019). "Singh and colleagues indicated the risk of serious infections is increased 30% during the treatment of anti-TNFα therapy, and common infections such as tuberculosis (TB), bacterial sepsis, Streptococcus pneumoniae, and Listeria monocytogenes might lead to hospitalization or death." (PMID 31194726, 2019). "Moreover, the clinical course of human TB shows that high levels of TNF-α have been associated with clinical decline in patients with TB, and higher secretion of TNF-α in humans could be associated with the haematogenous dissemination of M. tuberculosis to other organs." (PMID 29298876, 2018). "Because anti-TNF-α treatment is a known trigger of tuberculosis in humans, it is tempting to speculate that blocking of TNF-α may also abrogate the ability of later HSC progenitors and their lineage-positive cellular progeny, as well as MSCs, to control intracellular M. tuberculosis." (PMID 29471332, 2018). "The results we obtained on M. tuberculosis T-cells functional profile were also in agreement with those obtained in previous studies, as we found that CD4+ T-cell only producing TNF-α in response to PPD were increased in active TB patients." (PMID 30687314, 2018). "In accordance with the acquisition of this anti-inflammatory profile, TB-PE-induced FM secreted higher levels of IL-10 and lower levels of TNF-α upon stimulation with irradiated Mycobacterium tuberculosis (iMtb) than untreated cells." (PMID 29593722, 2018). "Tuberculosis is highly endemic in Ghana and yet, to the best of our knowledge, this study is the first to directly compare plasma levels of cytokines (IL-10, IFN-γ and TNF-α) in MDR-TB and DS-TB patients in the country." (PMID 30583589, 2018). "We have shown the ability of myeloid-specific TNF-deficient mice to survive the cerebral M. tuberculosis infection; however, we do not discriminate the important role of microglia as the main source of TNF in the brain during CNS-TB." (PMID 28280495, 2017). "This study aimed to determine the incidence and characteristics of active tuberculosis (TB) in patients treated with tumor necrosis factor (TNF) antagonists according to baseline latent tuberculosis infection (LTBI)." (PMID 28743918, 2017). "TNF-α encodes genes that codify TNF-α and TNF-β and is associated with severe infectious diseases, including malaria, mucocutaneous leishmaniasis, visceral leishmaniasis, and tuberculosis; the latter two diseases are associated with high TNF-α serum/plasma levels." (PMID 27051668, 2016). "However, 240 of the 258 patients had a history of anti-TNFα therapy, and therefore might have undergone tuberculosis screening before the previous treatment." (PMID 26961546, 2016).
tuberculosis (continued). "The patient tested positive for latent tuberculosis during TB skin testing routinely performed prior to anti-TNFα monoclonal antibody treatment." (PMID 27169677, 2016). "The time to tuberculosis onset after starting an anti-TNF agent provides an important clue from which its etiology can be discerned, since the clustering of cases shortly after the start of anti-TNF treatment is consistent with reactivation of latent infection." (PMID 27242697, 2016). "TNFα plays a critical role in the host response to tuberculosis (TB), having an essential role in the formation of the granuloma." (PMID 26635208, 2015). "Because of the risk of developing active tuberculosis (TB) with use of TNF-α antagonists, patients should be screened for latent tuberculosis infections (LTBI) before starting anti-TNF treatment." (PMID 25746854, 2015). "The interactions between M. tuberculosis and innate immune cells result in secretion of chemokines and cytokines, of which IFN-γ and TNF are particularly important in TB." (PMID 26019382, 2015). "Excessive production of TNF-α in active tuberculosis could contribute to tissue damage and lower concentrations, as observed in latent tuberculosis, would be responsible for maintaining the integrity of the granuloma, thus inhibiting the growth and spread of the mycobacteria." (PMID 26273486, 2015). "Similarly, as described for the use of corticosteroids, anti-TNF-α therapy may contribute to the response to tuberculosis therapy allowing the penetration of drugs into granulomas or improving their bactericidal activity against metabolically active bacilli." (PMID 26273486, 2015). "In order to elucidate the beneficial and detrimental roles of TNF-α in tuberculosis (TB) and other diseases for which the guinea pig is the small animal model of choice, recombinant guinea pig (rgp)TNF-α has been produced using prokaryotic expression systems." (PMID 25999670, 2015). "By the end of the follow-up period (218 to 1,264 days), four patients (4/137, 2.9%) developed active tuberculosis (TB) diseases during receiving TNF-α antagonist therapy." (PMID 26474294, 2015). "TNF inhibitor therapy may also result in active tuberculosis in humans carrying a latent infection." (PMID 25414636, 2014). "Immune therapy with anti-TNF antibody impairs antimicrobial activity of CD8+ T cells against M. tuberculosis and leads to increased risk of active TB." (PMID 23638187, 2013). "Secretion of TNF-α and IL-1β by Mtb-infected macrophages promotes necrosis, and this deregulation of cell death pathways may favor the release of viable bacilli, thus leading to the progression of tuberculosis." (PMID 24278357, 2013). "Any patient being considered for treatment with infliximab must be screened for untreated or latent Tuberculosis (TB) as reactivation of latent TB with use of anti-TNF-α agents has been described in the literature." (PMID 23533794, 2013). "The enhanced capacity of ΔmmaA4BCG/adjuvant and BCG/adjuvant vaccine formulations to induce elevated concentrations of the TNFα/IL-2 producing central memory T cells may contribute to the increased anti-tuberculosis protection seen after immunization with these preparations." (PMID 22442674, 2012). "IL-6 is required in the rapid expression of an initial protective IFN-γ response during M. tuberculosis infection, while TNF-α is important in the control of mycobacterial infections, as illustrated by the reactivation of TB in the use of anti-TNF drugs." (PMID 22058091, 2012). "Besides IFN-γ, TNF-α is also a key molecule in host immunity to tuberculosis." (PMID 23239994, 2012). "TNF was greatly reduced in TB/HIV co-infected individuals suggesting that HIV through TNF alters the immune response leading to impairment of the antituberculosis response." (PMID 21541068, 2011). "We also saw a tendency for TB cases infected with M. africanum to have increased TNF-α and IL-10 production compared to those infected with M. tuberculosis." (PMID 20811496, 2010).
tuberculosis (continued). "A paradoxical exacerbation of the signs and symptoms of tuberculosis may occur not only after tubercular therapy, but also after discontinuation of TNF-α inhibitors during the treatment of active tuberculosis, due to an enhanced antituberculous immune response." (PMID 19830122, 2009). "Tuberculosis (TB) in patients treated with TNF antagonists is characterised by a high frequency of extra-pulmonary and disseminated lesions and with few granulomas in involved organs." (PMID 16859506, 2006). "Due to the high global burden of latent Mycobacterium tuberculosis (TB) infections, prior to receiving anti-TNF therapy, patients testing positive for latent TB are given prophylactic treatment with anti-tuberculoid medications including the first described TB-selective antibiotic, Isoniazid." (PMID 39987456, 2025). "The frequency of M. tuberculosis-specific TNF-producing T cells may also assist in distinguishing latent from active TB." (PMID 40427602, 2025). "IFN-γ is a key pro-inflammatory cytokine produced by natural killer (NK) cells and T-helper-1 (Th1) cells that mediates immunity to TB, especially by activating macrophages and other immune cells, including IL-10 and tumor necrosis factor-alpha (TNF-α), to kill M. tuberculosis." (PMID 40487054, 2025). "Additionally, he was treated for latent tuberculosis (TB) and developed fulminant TB in the context of tumor necrosis factor inhibitor therapy, initially treated with ethambutol, isoniazid, moxifloxacin and pyrazinamide." (PMID 40301935, 2025). "Tuberculosis triggers a type 1 immune response characterized by IL-12, IFN-γ, and TNF-α production, while toxocariasis elicits a type 2 response, mediated by cytokines such as IL-4, IL-5, IL-13, and IL-33." (PMID 40943043, 2025). "MAIT cells show therapeutic potential for tuberculosis due to their ability to recognize Mtb antigens and produce pro-inflammatory cytokines (e.g., IFN-γ, TNF-α, IL-17A), which enhance antimycobacterial immunity." (PMID 40825006, 2025). "Future standard TB clinical evaluations should incorporate TNF-α periodic measures using bioassay or ELISA technologies as they may help in understanding the consequences of tuberculosis." (PMID 37007342, 2023). "Before initiating TNF-a inhibitor therapies such as golimumab, patients should be administered the protein-derived derivative (PPD) test for tuberculosis, have their varicella titers checked, and undergo hepatitis B and C serologic studies." (PMID 37511975, 2023). "A meta-analysis showed that treatment with anti-TNFα agents increased the risk of serious infections (OR: 1.72, 95% CI: 1.56–1.90, p < 0.00001) and an increase in cancer risk (OR: 1.36, 95% CI: 1.20–1.53, p < 0.00001), whereas the risk of tuberculosis was not significantly different." (PMID 37554981, 2023). "The preclinical and clinical development of AdV-based vaccines against tuberculosis underscored the significance of Th1 and CD8+T-cell responses, mediated through TNF alpha." (PMID 38213479, 2023). "On the other hand, CD8+ T cells have a protective role in immunity against TB; they can recognize infected cells and produce cytokines such as TNF and IFN-γ, lyse infected cells, and kill Mycobacterium tuberculosis (MTB), though not as effectively as CD4+ T cells." (PMID 37764989, 2023). "For instance, T cells in lung tissue in IL-32γ-transgenic mice infected with Mtb expressed higher levels of interferon gamma (IFN-γ) and TNF-α, and IL-32 was correlated with the balance of TH1/TH17 cytokines in the peripheral blood of tuberculosis patients." (PMID 35880892, 2022). "Given the critical function of TNF-a and IFN-g in protective immunity, it is possible that miR-144* has an effect on the development and outcome of tuberculosis." (PMID 35457250, 2022).
tuberculosis (continued). "In a multicenter retrospective pediatric tuberculosis European trials group (ptbnet) study, 19 cases of pediatric TB related to anti-tumor necrosis factor-alpha (anti-TNF-alpha) therapy were identified over 30 months; most patients had severe disease, and in one case, TB was diagnosed postmortem." (PMID 35215101, 2022). "It has already been shown that MMP-9 is overexpressed by monocytic cells in granulomas from tuberculosis cases and the TNF- α blockade decreased the expression of MMP-9 by 50% revealing that TNF- α is a key cytokine in monocyte-derived MMP-9 secretion." (PMID 35041718, 2022). "Arachidonic acid metabolism pathway, TNF, NF-κB, MAPK, non-small cell lung cancer, small cell lung cancer, IL17, tuberculosis, Th17, pertussis signal pathway, TLR, etc." (PMID 36685935, 2022). "In a recent report, the genes coding for IL-1β, TNF, IL-6, and JAK2 accounted for four of the seven most influential hub genes in the host response to tuberculosis disease." (PMID 36059986, 2022). "In the context of tuberculosis field, BCG has been demonstrated to be able to induce antigen-specific Th1-type CD4+ T cells with production of IFN-γ, IL-2 and TNF-α, which is considered to exert the protection against M.tb infection." (PMID 36387134, 2022). "Among them were diseases related to tuberculosis, hepatitis B, and trypanosomiasis, as well as cancer, PI3K Akt signaling, and TNF signaling pathways." (PMID 35371275, 2022). "theorized that early metformin treatment either 1) downregulates TNF-α and IFN-γ, or 2) suppresses anti-tuberculosis agents." (PMID 36159650, 2022). "IFN-γ and TNF-α were significantly higher in TB positive patients and it may act as a potential biomarker for diagnosis of genital tuberculosis." (PMID 35198736, 2022). "However, therapeutic TNF blockade is still not accurate, and often these anti-TNF treatments lead to serious and diverse effects that can even result in life threatening conditions, such as an increased risk of infections or tuberculosis reactivation." (PMID 34451529, 2021). "Because anti-TNF therapy increases the risk of active TB development through the reactivation of latent TB, guidelines recommend diagnosing and treating latent tuberculosis infection (LTBI) before starting anti-TNF therapy." (PMID 34670529, 2021). "Among the enriched signalling pathways in lung tissue and blood, three are considered to be significantly related to tuberculosis, including the NOD‐like receptor signalling pathway, Toll‐like receptor signalling pathway and TNF signalling pathway." (PMID 34213077, 2021). "Previous studies have verified some cytokine secretion profiles from CD4+ T cells in patients with tuberculosis, such as IFN-γ+, TNF-α, IL-2 and CD27." (PMID 34176483, 2021). "Upregulated hub network 2 was involved in regulating NF-kappa B signaling pathway, TNF signaling pathway, HIF-1 signaling pathway, Toll-like receptor signaling pathway, tuberculosis, legionellosis, and complement and coagulation cascades." (PMID 32908583, 2020). "Activation of latent tuberculosis following IL-1 receptor antagonist therapy has also been reported, but the risk of TB reactivation has not been thoroughly studied for non-TNF antagonists." (PMID 32764422, 2020). "In algorithms combining young age, positive skin test results, and elevated CFPS TNF-α, IFN-γ, and IL-10 responses, the positive predictive values for co-prevalent and incident tuberculosis were 40 and 25%, respectively." (PMID 32736606, 2020). "Latent tuberculosis can reactivate and lead to active TB disease if the immune system is weakened, with risk factors including HIV infection, organ transplantation that involves immunosuppression, tumor necrosis factor alpha-blocker treatments, chronic renal failure, and hemodialysis." (PMID 33315067, 2020). "Interestingly, those patients treated with a TNFα antagonist displayed a reactivation of latent tuberculosis (TB) or even an aggravation of primary TB." (PMID 31739600, 2019).